DUX4 (double homeobox 4)
Diseases named in the same sentence as DUX4 in open-access papers (continued):
Sharing a sentence is not in itself a finding about the gene and the disease.
cancer (48 papers, 2012 to 2026). A tumor composed of atypical neoplastic, often pleomorphic cells that invade other tissues. "In some cancers caused by DUX4 rearrangement, this chromatin remodeling promotes tumor progression by increasing the ability of cancer cells to replicate." (PMID 40427614, 2025). "DUX4 is involved in the activation of the zygote genome and then facilitates the establishment of totipotency in pre-implantation embryos, whereas the misexpression of DUX4 is associated with different types of cancer." (PMID 40427614, 2025). "DUX4-mediated retrotransposon activation during early development serves as a precursor to the mechanisms underlying genomic instability in cancer, wherein similar retrotransposon dysregulation contributes substantially to cancer pathogenesis." (PMID 40427614, 2025). "DUX4 expression in cancers was associated with decreased major histocompatibility complex class I (MHC-I) expression, resistance to checkpoint inhibitors, and decreased patient survival rates." (PMID 37747887, 2023). "Genes associated with the immune system are also dysregulated by DUX4 in myogenic cells, and DUX4 promotes immune evasion in cancer cells by blocking interferon-γ regulated major histocompatibility complex class 1 genes, so reducing antigen presentation." (PMID 32242220, 2020). "In addition to a role in FSHD, recent analysis of nearly 10,000 cancer transcriptomes from 33 different cancer types revealed DUX4 to be one of the most commonly expressed cancer-associated genes." (PMID 37747887, 2023). "DUX4 is also aberrantly re-expressed following infection by all viruses of the Herpesviridae family, which in humans are associated with several diseases, including mononucleosis, encephalitis, varicella and a range of malignancies." (PMID 34943834, 2021). "The mechanism of DUX4 upregulation in cancer cells remains unknown, although it has been proposed that it is linked to demethylation of the 3.3 kb repeats harboring DUX4 ORF." (PMID 27556182, 2016). "Furthermore, the common DUX4 regulation mechanism may reveal potential targets for cancer treatment, especially in cancers caused by abnormal embryonic program reactivation." (PMID 40427614, 2025). "In carcinogenesis, DUX4 expression leads to the reactivation of a developmental program that promotes cancer cell stemness." (PMID 40427614, 2025). "DUX4 expression in cancer cells induces an early embryonic program that promotes metastasis while simultaneously suppressing immune responses, thereby enhancing tumor growth." (PMID 40427614, 2025). "Elucidating how DUX4 mediates embryonic gene activation and tumor progression will shed light on the mechanisms by which cancer cells hijack developmental pathways to promote proliferation and metastasis." (PMID 40427614, 2025). "Particularly, DUX4, a transcription factor that is specifically expressed during early embryonic development, is highly expressed in cancer cell lines." (PMID 40427614, 2025). "This conceptual framework would provide us with a more comprehensive understanding of the developmental origins of cancer, contextualizing our DUX4 findings within a broader paradigm of embryonic program reactivation in tumorigenesis." (PMID 40427614, 2025). "To this end, we reanalyzed sequencing data from the International Cancer Genome Consortium and classified tumors for DUX4 expression by a DUX4 score that includes expression of DUX4 and known DUX4 target genes." (PMID 39814710, 2025). "The reactivation of DUX4 in cancer cells has significant clinical implications, particularly concerning immune evasion and tumor progression." (PMID 40427614, 2025). "As we continue to explore the complex relationship between cancer and embryogenesis, elucidating the role of DUX4 in linking these two processes will be critical for developing targeted therapies that exploit developmental pathways." (PMID 40427614, 2025).
cancer (continued). "For instance, the transient expression of DUX4 in cancer cells induces a metastable early embryonic stem cell program, including the activation of zygotic gene activation (ZGA) and eight-cell-like (8C-like) transcriptional programs." (PMID 40427614, 2025). "In cancer, the ability of DUX4 to promote cell proliferation at the expense of differentiation has been implicated in tumor progression." (PMID 40427614, 2025). "As a target gene of DUX4, ZSCAN4, which is essential for telomere extension in embryonic stem cells, is also activated in numerous cancers that express DUX4, potentially enhancing tumor replicative capacity." (PMID 40427614, 2025). "In the context of oncogenesis, DUX4’s expression in cancer cells has been shown to contribute to immune evasion, a mechanism that allows tumors to avoid detection by the host’s immune system." (PMID 40427614, 2025). "In cancer contexts, DUX4 has also been shown to suppress MHC class I expression, contributing to immune evasion and possibly promoting tumor proliferation by reducing anti-tumor immune responses." (PMID 40427614, 2025). "DUX4 modulates the expression of multiple downstream target genes, inducing a stem cell-like state that enables cancer cells to evade differentiation signals while maintaining proliferative capacity." (PMID 40427614, 2025). "This evasion mechanism helps cancer cells to survive and proliferate in hostile tumor microenvironments, highlighting DUX4’s role in supporting cancer cell growth." (PMID 40427614, 2025). "This DUX4-induced excessive or deregulated proliferation also contributes to tumorigenesis, which is seen in the context of cancer." (PMID 40427614, 2025). "In this review, we position DUX4 as a unique “developmental hijacker” that orchestrates the reactivation of cleavage-stage transcriptional programs in cancer." (PMID 40427614, 2025). "DUX4-expressing cancers had lower measures of the gene signature, consistent with decreased CD8+ T cell infiltration into the tumor." (PMID 38829686, 2024). "Given the correlation between cancer DUX4 expression and signatures of anti-tumor immune response suppression, we sought to understand if DUX4 expression in patient tumors was associated with accompanying changes to overall survival during PD-L1 inhibition." (PMID 38829686, 2024). "(B) The proportion of DUX4-expressing cancers in TCGA (purple shading) and metastatic (red shading) cancers." (PMID 38829686, 2024). "To assess the prevalence of DUX4-expressing human malignancies, we performed a large-scale analysis of publicly available RNA-seq data across diverse cancer types." (PMID 38829686, 2024). "HERV-L and HERV-E, which are activated by the TFs DUX4 and HIF, respectively, are associated with cancer." (PMID 38540701, 2024). "Overall, our analyses demonstrate a significant and robust decrease in survival attributable to DUX4 expression in advanced cancers." (PMID 38829686, 2024). "This author is an inventor on a patent application submitted by Fred Hutchinson Cancer Center that covers DUX4 expression in cancers and response to immunotherapy (PCT/US2019/043396)." (PMID 38829686, 2024). "Activation of DUX4 during the early stages of cancer has been shown to remove the cell surface proteins the immune system uses to recognize tumors." (PMID 38829686, 2024). "The RSF model predicted worse survival outcomes in patients with DUX4-expressing cancers compared to their DUX4-silent counterparts." (PMID 38829686, 2024). "Second, the pervasive expression of DUX4 in all the metastatic cohorts we examined exhibits its potential as a pan-cancer biomarker." (PMID 38829686, 2024). "DUX4 is also known upregulated in a variety of human cancers, and more work is needed to dissect the roles in virus induced cancer regarding viral replication and cancer development." (PMID 37876935, 2023).
cancer (continued). "As a result, combining our knowledge of DUX4 biology in cancer, FSHD, and embryonic development will be critical to understand conserved pathways and to develop innovative therapeutic approaches." (PMID 37747887, 2023). "Our current findings also provide a molecular mechanism for the suppression of IFNγ-stimulated genes in DUX4-expressing cancers." (PMID 37092726, 2023). "Cancers expressing DUX4 had diminished IFNγ-induced MHC class I expression, reduced anti-tumor immune cell infiltration, and showed resistance to immune checkpoint blockade." (PMID 37092726, 2023). "We also provide evidence of decreased de novo protein synthesis in FSHD and cancer cells endogenously expressing DUX4." (PMID 37747887, 2023). "Full-length DUX4 expression in diverse cancer types is strongly correlated with increased expression of high-confidence DUX4 targets activated in the embryo." (PMID 37747887, 2023). "This work provides new insights into cellular reprogramming and highlights opportunities for FSHD and cancer treatments targeting DUX4 and its downstream effectors." (PMID 37747887, 2023). "Reanalysis of almost 10.000 cancer transcriptomes from The Cancer Genome Atlas (TCGA) showed DUX4 re-expression in many human cancers." (PMID 38168299, 2023). "DUX4 (double homeobox 4), a pre-implantation embryonic transcription factor normally silenced in somatic tissues, was found reactivated in many cancers." (PMID 35343573, 2022). "Recent searches on cancer have also revealed that DUX4 expression was present in most of the cancer cell types suggesting new roles for DUX4." (PMID 34854471, 2022). "Embryonic cells, cancer cells and testis cells that show DUX4 expression are pluri-multipotent cells." (PMID 34854471, 2022). "Of note, plasmid-mediated overexpression of DUX4 in human epithelial carcinoma HEp-2 cells leads to mis-localization of the inner nuclear envelope protein, emerin." (PMID 35191484, 2022). "In this context, DUX4 drives an aberrant program of embryonic gene expression and provides a distinct advantage to cancer cells, allowing suppression of MHC class I-dependent antigen presentation, immune evasion, and resistance to immune checkpoint blockade." (PMID 34943834, 2021). "In DUX4-positive cancers, a reduced immune infiltration is in contrast with the frequent presence of inflammation and lymphocytic infiltration observed in FSHD in which the inflammatory response has been directly associated with DUX4 expression." (PMID 34943834, 2021). "More recently, DUX4 activation gained a particular interest across cancer research, as DUX4 expression in tumours results in immune evasion." (PMID 32731450, 2020). "Other genes like CCNE1, SENP5, FN1, KMT2B, and DUX4 were alsoidentified by HGT-ID; these genes were previously reported to be associated with tumorigenesis or cancer invasion." (PMID 30016933, 2018). "This novel framework emphasizes that DUX4 may serve as a master regulator at the nexus of embryonic and cancer cell states, with capabilities that distinguish it from other developmental factors." (PMID 40427614, 2025). "Moreover, DUX4 de-repression in cancer cells results in the suppression of antigen presentation and promotes immune evasion." (PMID 41211819, 2025). "By contrast, gene fusion analysis (using both short-read/long-read WGS and RNA-seq) can be used to detect DUX4-r B-ALL even where diagnostic information is unavailable, and can also detect DUX4 rearrangements occurring in non-leukaemic cancers." (PMID 40940582, 2025). "Additionally, the DUX4 (double homeobox 4) TF is expressed during specific windows of human embryogenesis [and by many human cancers and viruses (reviewed in 123)] and is required for proper maturation of pre- and postimplantation embryos." (PMID 40440481, 2025).
cancer (continued). "Through examining DUX4, this review underscores the importance of developmental mechanisms in cancer biology, suggesting that the insights gained from studying embryonic processes may provide novel therapeutic strategies." (PMID 40427614, 2025). "DUX4 functions as a crucial transcription factor involved in early embryogenesis, but its impact on cell proliferation extends beyond development and plays an essential role in various diseases, particularly in muscle and cancer pathologies." (PMID 40427614, 2025). "In the future, this work could be extended to see if DUX4 could be used as a prognostic tool for other types of cancer." (PMID 38829686, 2024). "We hypothesized that DUX4 expression in these cancers will generate related transcriptomic signals consistent with CD8+ T cell exclusion from the tumor." (PMID 38829686, 2024). "We speculate that DUX4-expressing cancer cells might hijack these mechanisms to enhance cellular plasticity and create an immunosuppressive milieu, thereby promoting tumorigenesis and therapeutic resistance." (PMID 37747887, 2023). "For a variety of human cancers, the expression of DUX4 in malignant cells has been reported." (PMID 37876935, 2023). "In addition to its role in ZGA and in the development of FSHD, it was published that DUX4 also plays an important role in a variety of human cancers." (PMID 38168299, 2023). "B-ALL is one of the other newly discovered DUX4-expressing cancer types." (PMID 34854471, 2022). "DUX4 may promote immune evasion in cancer by blocking interferon‐γ‐regulated MHC class I genes, so reducing antigen presentation to CD8+ T cells." (PMID 34151531, 2021). "Understanding why early embryos and cancer cells can tolerate DUX4 expression, while DUX4 is highly toxic to muscle cells could provide possible treatments for FSHD." (PMID 34943834, 2021). "Additionally, CAMK2A, the third most up-regulated gene at DUX4 relapse, acts as an anti-apoptosis regulator by activating NF-kB in metabolic stress-resistant cancer stem cells." (PMID 30862934, 2019). "DUX4 induces a metastable early embryogenic stem cell transcription (ZGA, 8 cell-like program, markers of early embryogenic lineages) and causes immune evasion of the cancer cells by reducing antigen presentation, since it prevents IFN-γ-mediated induction of MHC class I genes." (PMID 40855454, 2025). "For example, the Pelops tool has successfully identified DUX4 fusion events in other cancer types across Genomics England cohorts, many of which were not previously known to be associated with DUX4 rearrangements (Alona Solinsky, personal communication, January 2025)." (PMID 40940582, 2025). "Since DUX4 is typically silent in most healthy tissue contexts outside the cleavage-stage embryo, we investigated if artifacts related to sequencing and sample processing could account for the observed high rates of DUX4 expression in metastatic vs. primary cancers." (PMID 38829686, 2024). "However, it remained unclear whether DUX4 changes the response to immunotherapy in more advanced cancers which have begun to spread and metastasize to other parts of the body." (PMID 38829686, 2024). "In addition there are reports of DUX4 expression in human cancer." (PMID 37876935, 2023). "Additionally, the transcription factor double homeobox 4 (DUX4) has been shown to block the IFNγ mediated upregulation of tsMHC-I in numerous cancer types in vitro resulting in failure to respond to anti-CTLA-4 and anti-PD-1 therapy and decreased overall survival." (PMID 35296095, 2022). "Moreover, therapies developed for FSHD could be used in DUX4-dependent cancers (PMID: 34642317) or vice versa (see Section 10)." (PMID 34943834, 2021). "Despite the ability of DUX4 to facilitate cancer progression, cancer risk in FSHD is not elevated above that of the general population, though recent findings suggest that gastrointestinal cancers in particular may be more prevalent among FSHD adults (>40 years) than in non-affected adults." (PMID 40940582, 2025).
cancer (continued). "(C) DUX4 expression values (TPM, transcripts per million) in TCGA (purple shading) and advanced metastatic (red shading) cancer cohorts analyzed in our study." (PMID 38829686, 2024). "Endogenous expression of DUX4 in human FSHD myotubes and cancer cell lines also correlated with reduced protein synthesis and MHC-I presentation." (PMID 37747887, 2023). "These reinforce the conceptual framework that cancer frequently hijacks embryonic transcriptional programs, not just through DUX4 but through multiple transcription factor networks that normally operate during development." (PMID 40427614, 2025). "One of the primary ways DUX4 achieves immune evasion is by suppressing the expression of major histocompatibility complex (MHC) class I molecules, which are essential for the immune system to recognize and attack cancer cells." (PMID 40427614, 2025). "Although the aberrant expression of DUX4 has been predominantly studied in the context of FSHD, recent studies have demonstrated that DUX4 is ectopically expressed in various cancers and plays a critical role in tumor progression, immune evasion, and therapy resistance." (PMID 40427614, 2025). "This contrast between WT CIC acting as a tumor suppressor and CIC::DUX4 being an oncogene provides a rare opportunity to take knowledge learned from the natural evolution of CIC inactivation in WT CIC cancers and apply those strategies to potentially disable the CIC::DUX4 fusion oncoprotein." (PMID 39530749, 2024). "Examining the absolute effects of DUX4 expression on survival, the RSF model predicted an approximately 20% decrease in both 1- and 1.5-year survival probabilities in patients with DUX4-expressing cancers." (PMID 38829686, 2024). "These analyses suggest that DUX4 expression in the metastatic context induces an immunosuppressive gene expression program, concordant with its established function in inhibiting JAK–STAT signaling in primary cancers." (PMID 38829686, 2024). "Together, these results show that endogenous DUX4 expression in 2 independent cell types, FSHD muscle cells and SuSa germinoma cells, suppress protein synthesis and that this correlates with suppression of IFNγ-induced MHC-I expression in cancer cells." (PMID 37747887, 2023). "Indeed, DUX4, one of the transcription factors we found upregulated in SBT-MP and maintained in LGSC, promotes cancer immune evasion." (PMID 38014221, 2023). "Clarifying the role of DUX4 in potent healthy somatic cells might provide key information for the pathophysiology of B-ALL, other DUX4 related cancers, and FSHD." (PMID 34854471, 2022). "These feasibility of targeting DUX4 experiments were initially tested in a non-myogenic carcinoma cell line that we have previously characterized." (PMID 34131248, 2021). "To further characterize the subgroups with DUX4-IGH and ZNF384 rearrangements, we utilized previously published targeted exome sequencing data including 872 cancer genes and array-based copy number data derived from the HumanMethylation 450 k arrays from the same patients." (PMID 28806978, 2017). "The DUX4 target HSATII is expressed in a number of cancers, and it has been shown that mouse cells lacking the genome caretaker gene Brca1 aberrantly transcribe satellite sequences leading to genome instability." (PMID 24278031, 2013). "A large number of other DUX4 targets are known “cancer testis antigens” (CTAs): genes normally expressed only in testis but de-repressed in some cancers, eliciting an immune response." (PMID 24278031, 2013). "Interestingly, in line with a recent report, half of our T2-STIR + FSHD samples showed overexpression of DEFB103B, which is a DUX4-dependent gene involved in the modulation of both adaptive and innate immune responses, and PRAME family cancer testis antigens." (PMID 22719944, 2012).